KCTD20 (potassium channel tetramerization domain containing 20)
Description:
Promotes the phosphorylation of AKT family members.
Synonyms: C6orf69; dJ108K11.3; MGC14254
Tractability: PROTAC: ubiquitination databases record sites on it.
Gene: Protein-coding gene on chromosome 6 (36,442,767 to 36,491,143, forward strand). Ensembl gene ENSG00000112078.
Subcellular location: Cytoplasm
Subcellular location (Human Protein Atlas): Endoplasmic reticulum; Nuclear speckles
Gene Ontology:
Molecular function: identical protein binding
Biological process: positive regulation of phosphorylation
Cellular component: cytoplasm
Genetic constraint (gnomAD): Loss-of-function variants: 25 observed, 31.94 expected, observed/expected ratio (o/e) 0.78, 90% interval 0.57 to 1.09. The upper end of that interval is the gene's LOEUF score, 1.09, which puts it in group 4 of 6, group 1 being the genes least tolerant of losing a copy. Missense variants: 346 observed, 455.25 expected, observed/expected ratio (o/e) 0.76, 90% interval 0.69 to 0.83. Synonymous variants: 129 observed, 161.45 expected, observed/expected ratio (o/e) 0.8, 90% interval 0.69 to 0.93.
Homologues: Orthologues: chimpanzee KCTD20 (99% identical), macaque KCTD20 (95% identical), pig KCTD20 (95% identical), dog KCTD20 (93% identical), guinea pig KCTD20 (93% identical), mouse Kctd20 (91% identical), rat Kctd20 (89% identical), zebrafish KCTD20 (52% identical), Drosophila melanogaster mri (45% identical), Caenorhabditis elegans btbd-10 (43% identical). Paralogues in human: BTBD10 (61% identical).
Diseases named in the same sentence as KCTD20 in open-access papers:
KCTD20 is named in the same sentence as 6 diseases in open-access papers, as found by Europe PMC text mining. Sharing a sentence is not in itself a finding about the gene and the disease. The quoted sentences say what the papers report.
non-small cell lung carcinoma (2 papers, 2021). A group of at least three distinct histological types of lung cancer, including non-small cell squamous cell carcinoma, adenocarcinoma, and large cell carcinoma. "The BTBD10 subunit (KCTD20) enhanced the proliferation and invasion of non-small cell lung (NSCLC) cancer by increasing the phosphorylation level of Akt." (PMID 35059434, 2021). "A recent study correlates high KCTD20 expression with advanced non-small cell lung cancer (NSCLC), characterized by positive regional lymph node metastasis and poor prognosis." (PMID 34001146, 2021).
Lyme borreliosis (1 paper, 2024). "A second GWAS published shortly later replicated the rs2232950 hit and identified rs1061632—an expression quantitative trait locus for KCTD20 and ETV7, as associated with Lyme borreliosis." (PMID 39140751, 2024).
tumor (1 paper, 2021). "Recently, scientists found that KCTD20) enhanced the proliferation and invasion of NSCLC via increasing the phosphorylation level of Akt, indicating a potential role of BTBD10 in tumor diseases." (PMID 35059434, 2021).
KCTD20 also shares sentences with these, for which no sentence is quoted: cocaine dependence (1 paper); glioma (1); rheumatic disease (1).